TIMCC (TIM double twin CX3C motif chaperone)
Description:
Plays a role in proteostasis of the mitochondrion intermembrane space and counteracts aggregation of certain proteins. Required for mitochondrial oxidative phosphorylation.
Synonyms: FAM136A; FLJ14668
Tractability: PROTAC: ubiquitination databases record sites on it; its protein half-life has been measured.
Gene: Protein-coding gene on chromosome 2 (70,295,976 to 70,302,067, reverse strand). Ensembl gene ENSG00000035141.
Subcellular location: Mitochondrion intermembrane space
Subcellular location (Human Protein Atlas): Mitochondria
Gene Ontology:
Molecular function: protein binding
Cellular component: cytoplasm; mitochondrial intermembrane space; mitochondrion
Genetic constraint (gnomAD): Loss-of-function variants: 25 observed, 21.38 expected, observed/expected ratio (o/e) 1.17, 90% interval 0.85 to 1.63. The upper end of that interval is the gene's LOEUF score, 1.63, which puts it in group 6 of 6, group 1 being the genes least tolerant of losing a copy. Missense variants: 338 observed, 331.19 expected, observed/expected ratio (o/e) 1.02, 90% interval 0.93 to 1.12. Synonymous variants: 119 observed, 128.34 expected, observed/expected ratio (o/e) 0.93, 90% interval 0.8 to 1.08.
Homologues: Orthologues: chimpanzee FAM136A (100% identical), macaque FAM136A (56% identical), dog FAM136A (54% identical), mouse Fam136a (51% identical), guinea pig FAM136A (50% identical), rat Fam136a (50% identical), tropical clawed frog fam136a (41% identical), zebrafish fam136a (23% identical), Drosophila melanogaster CG5323 (21% identical), Caenorhabditis elegans famh-136 (20% identical), Drosophila melanogaster CG5327 (19% identical), Drosophila melanogaster CG12661 (16% identical).
Diseases named in the same sentence as TIMCC in open-access papers:
TIMCC is named in the same sentence as 13 diseases in open-access papers, as found by Europe PMC text mining. Sharing a sentence is not in itself a finding about the gene and the disease.
TIMCC shares sentences with these, for which no sentence is quoted: Meniere disease (3 papers); tumor (2); adenocarcinoma (1); carcinoma (1); liver cancer (1); lung adenocarcinoma (1); lung carcinoma (1); lymph node metastasis (1); myasthenia gravis (1); myxofibrosarcoma (1); osteoarthritis (1); sarcoma (1); stomach adenocarcinoma (1).